IL5 (interleukin 5)
Diseases named in the same sentence as IL5 in open-access papers (continued):
Sharing a sentence is not in itself a finding about the gene and the disease.
atherosclerosis (45 papers, 2014 to 2025). A disease characterized by the build-up of fatty material and calcium deposition in the arterial wall resulting in partial or complete occlusion of the arterial lumen. "As the major and direct consequence of dyslipidemia, atherosclerosis can be attenuated by Th2-associated cytokines, such as IL-5 and IL-13, according to previous studies." (PMID 35265637, 2022). "Circulating concentrations of novel CVD risk biomarkers including interleukin-6 and interleukin-5 adipokines were mostly similarly associated with both endothelial activation and atherosclerosis amongst African black and white RA patients." (PMID 25157371, 2014). "By contrast, circulating concentrations of novel CVD risk biomarkers including interleukin-6 and interleukin-5 adipokines were mostly similarly associated with both endothelial activation and atherosclerosis amongst African black and white RA patients." (PMID 25157371, 2014). "In contrast, in IL-5 deficient models, atherosclerosis progression was prominent." (PMID 39944697, 2025). "However, a lack of IL-4 just minimally changes how atherosclerosis develops, IL-5 deficiency, however, has been proven to hasten atherosclerosis." (PMID 37662948, 2023). "It is reported that a deficiency of IL-5 can result in accelerated atherosclerosis in ApoE−/− mice." (PMID 31011288, 2019). "However, other studies have reported a correlation between elevated IL-5 levels and the risk of coronary events, as well as a negative correlation between plasma IL-5 concentrations and subclinical atherosclerosis." (PMID 31130914, 2019). "First, due to enhanced expression of PU.1, KLF4, MafB, and LXRα, these cells acquired antiinflammatory properties, including the increased secretion of IL-10, IL-1RA, and IL-5, aiding to resolve inflammation and protect against atherosclerosis." (PMID 39531328, 2024). "Th2 cells, known for their anti-inflammatory properties, can delay or potentially reverse atherosclerosis progression, primarily via the secretion of cytokines like interleukin 4 (IL-4), interleukin 5 (IL-5), and interleukin 13 (IL-13)." (PMID 39200308, 2024). "Interleukin‐5 (IL‐5) has been reported to be involved in cardiovascular diseases, such as atherosclerosis and cardiac injury." (PMID 38963241, 2024). "This is indirectly confirmed by the fact that autoantibodies against IL-5, suppressing its function, accelerate the development of atherosclerosis." (PMID 37047399, 2023). "Interleukin-5 (IL-5) and interleukin-10 (IL-10) were thought to be protective factors against atherosclerosis." (PMID 35651907, 2022). "The main Th2 cytokine is IL-4, which suggests a disease‐promoting effect, while Th2-secreted IL-5 and IL-13 have a protective effect in atherosclerosis patients." (PMID 34915859, 2021). "In atherosclerosis, CD4+ Th2 immune responses are considered to be anti-inflammatory due to the secretion and action of IL-4 or IL-5, linked to B cell activation and antibody production." (PMID 30979943, 2019). "Studies have also reported that IL-13, IL-5 and IL-4 all participate in the pathological process of atherosclerosis, which is the major pathogenesis of CAD12,25–27." (PMID 29670225, 2018). "IL-5 has been suggested to play a role in protection against atherosclerosis in humans due to the stimulation of B1 cells and the production of IgM antibodies to OxLDL." (PMID 29329335, 2018). "Pg-immunized mice with extensive atherosclerosis had lower IL-5, IL-10 and IL-22 levels than those with less atherosclerosis." (PMID 29329335, 2018). "We designed reconstitution experiments to address the specific roles of ILC2-derived IL-5 or IL-13 in the control of atherosclerosis." (PMID 28589929, 2017). "On the contrary, in the development of atherosclerosis, IL-33 markedly increased the levels of IL-4, IL-5, and IL-13, and decreased the level of IFN-γ." (PMID 28423665, 2017).
atherosclerosis (continued). "Crucially however, recipients of ILC2KO/IL-5− BM, which are replete with IL-5-deficient ILC2, developed severe atherosclerosis comparable to the full ILC2 knockout condition." (PMID 28589929, 2017). "As was observed with the ILC2-specific IL-5 deficiency, the inability of ILC2 to produce IL-13 significantly increased atherosclerosis in the aortic arch." (PMID 28589929, 2017). "Moreover, the protective effects against atherosclerosis of IL-33 were hindered by combining it with a neutralizing anti-IL-5 antibody, indicating that the assistance provided by IL-33 in vivo is possibly mediated through an IL-5-driven response." (PMID 39844544, 2025). "Th2 cells secrete IL-4, IL-5 and IL-13, among which IL-5 and IL-13 have been shown to have a protective effect on atherosclerosis, and IL-13 can reduce the infiltration of macrophages in plaques by decreasing the expression of vascular cell adhesion molecule-1 (VCAM-1)." (PMID 41268556, 2025). "The main pathways involved include the focal adhesion‐PI3K‐Akt‐mTOR‐signaling pathway; AhR; fluid shear stress and atherosclerosis; protein processing in endoplasmic reticulum; thermogenesis; adipogenesis; and several inflammatory‐related pathways (IL‐5, IL‐2, TGF‐β receptor, and IL‐6 signaling)." (PMID 41169019, 2025). "Previous studies have reported that increased IL‐5 expression can significantly inhibit both Ang II‐ and high‐fat diet‐induced atherosclerosis in mice, suggesting that IL‐5 may be a regulatory target for atherosclerosis." (PMID 38963241, 2024). "Furthermore, Th1 cells are the main type of CD4+ T cells in AS, which produce a large number of pro-inflammatory cytokines, while Th2 cells can produce IL-13 and IL-5 to antagonize atherosclerosis." (PMID 36969166, 2023). "Overall, it is intriguing that IL-1α may exert effect on progression of atherosclerosis in Rgp44-immunized mice whereas the anti-inflammatory cytokines IL-5 and IL-10 are crucial for possible atheroprotection in Pg-immunized mice." (PMID 29329335, 2018). "ILC2-derived cytokines (IL-5 and IL-13) are therefore vital components controlling the progression of atherosclerosis, particularly IL-13 which may alter macrophage phenotype, and its absence leads to larger and potentially more vulnerable plaques." (PMID 28589929, 2017). "IL-33 may play a protective role in the development of atherosclerosis via the induction of IL-5 and ox-LDL antibodies." (PMID 27579324, 2016). "Interestingly, IL-33 has been suggested to play a protective role in the development of atherosclerosis by inducing IL-5 and oxidized LDL specific antibodies." (PMID 25629516, 2015). "In addition, IL-33 has been suggested to play a protective role in the development of atherosclerosis via the induction of IL-5 and ox-LDL antibodies." (PMID 25629516, 2015). "In addition, blockade of OX40L reduced experimental atherosclerosis, induced IL-33 production by antigen presenting cells resulting in an increase of IL-5 and natural IgM specific for oxidized LDL." (PMID 25629516, 2015). "Although IL-4 and IL-5 protect against atherosclerosis, IL-9 may promote atherosclerosis." (PMID 39684449, 2024). "IL-5 may play a role in the development of human atherosclerosis." (PMID 37047399, 2023). "Interestingly, earlier studies pointed out that IL-33 could attenuate the occurrence and development of atherosclerosis by inducing IL-5 and ox-LDL antibodies." (PMID 33854693, 2021). "Thus, augmentation of ILC2 and ILC2-derived IL-5 or IL-13 on top of Treg expansion might constitute a potentially attractive double-hit therapy to limit accelerated atherosclerosis." (PMID 28589929, 2017).
atherosclerosis (continued). "We found an expansion of ILC2s in the spleen, increased levels of IL-5, elevated levels of plasma anti-phosphorylcholine (PC) natural IgM antibodies accompanied with reduced plaque area in the aorta of IL-25 treated mice, indicating that IL-25 protects against atherosclerosis development." (PMID 25629516, 2015). "In experimental models, IL-5 was shown to induce the activation of adaptive immunity with IgM epitopes specific to ox-LDL, inhibiting atherosclerosis progression." (PMID 39944697, 2025). "Decreased IL‐5 expression has been observed in human CHF, high‐fat diet‐induced mouse atherosclerosis and doxorubicin‐induced mouse acute cardiac injury." (PMID 38963241, 2024). "Recent studies have demonstrated that innate lymphoid cell type-2 derived IL-13 and IL-5 cytokines in PVAT are important to maintain atheroprotective IgM producing B-1 cells in PVAT and attenuate diet induced atherosclerosis." (PMID 28970806, 2017). "Using mice specifically deficient in ILC2, we show that endogenous ILC2 perform a central role in controlling the progression of atherosclerosis and this effect is in part dependent on ILC2-derived IL-5 and IL-13." (PMID 28589929, 2017). "The present findings demonstrate that IL-25 has a protective role in atherosclerosis mediated by innate responses, including ILC2 expansion, increased IL-5 secretion, B1a expansion and natural anti-PC IgM generation, rather than adaptive Th2 responses." (PMID 25629516, 2015). "Other reported positive regulators of IgM levels in atherosclerosis like IL5 and BAFF were significantly upregulated in spleens of No Tfh compared to WT Tfh mice." (PMID 38381113, 2024). "Also in a clinical study, plasma IL-5 levels were found to be related to levels of IgM antibodies recognizing oxidized LDL and to decreased subclinical atherosclerosis." (PMID 25629516, 2015). "While IL-33 exacerbates autoimmune collagen-induced arthritis via mast cell degranulation 22, it also promotes type 2 immune responses with the production of high levels of IL-5 and IL-13 20 and drives M2 macrophage differentiation thus protecting mice from EAE 26 and atherosclerosis." (PMID 25116404, 2014). "Atherosclerosis development has also been reported in mice lacking IL-5 production." (PMID 38674885, 2024). "Additionally, ILC2KO mice reconstituted with IL-5+ ILC2 did not develop increased atherosclerosis compared to ILC2WT mice, further supporting the requirement for a competent ILC2 population to limit atherogenesis." (PMID 28589929, 2017). "In this study, mice in the ApoEST2DKO group, with significant atherosclerosis development, showed increased VCAM1 and ICAM1 levels and a non-significant but decreasing trend in IL-4 and IL-5, consistent with previously reported results." (PMID 38674885, 2024).
depression (44 papers, 2012 to 2025). "Whilst the Th2-associated cytokine IL-5 was elevated in depression (SMD = 0.36 [95% CI 0.05 to 0.66], p = 0.02), Th2 cell counts (p = 0.97), Th1 cell counts (p = 0.17) and interferon-γ (p = 0.22) were not." (PMID 39012496, 2024). "In a human study, elevated levels of Il5 were associated with an increased likelihood of major depressive disorder." (PMID 29529077, 2018). "Furthermore, our finding that increases in self-reported sleep problems were associated with higher measures of depression, anxiety, IL-5, and IL-10 are similarly consistent with the consensus of these reviews." (PMID 33598780, 2021). "Moreover, high levels of IL-5 have been associated with the likelihood of suffering major depression." (PMID 30662368, 2018). "Several studies have reported elevated IL-5 levels in patientswith depression, and demonstrated that both IL-5 and GM-CSF levels significantlydecrease following antidepressant treatment." (PMID 40926813, 2025). "In our review, we noticed that IL-5 decreased with the administration of the SSRIs escitalopram (one study, moderate depression) and with ketamine (one study, treatment-resistant depression)." (PMID 40573262, 2025). "Patients with anxiety and depressive disorders have increased levels of pro-inflammatory cytokines (e.g., TNFα, IL-1α, IL-1β, IL-4, IL-5, IL-6, IL-12, and interferon [IFN]-γ) and C-reactive." (PMID 39803412, 2025). "Depression was associated with a lower IFN-γ level and an elevated IL13 level; the functions of IL13 have similarities with the role of IL5." (PMID 36009493, 2022). "We suggest that the mechanisms underlying the effect of reslizumab on the pathophysiology of depression involve IL5." (PMID 36009493, 2022). "TNF-α, IFN-γ, IL-5, IL-12 and IL-13 were also related to the severity of depressive symptoms, as well as the somatic–affective and cognitive dimensions of depression." (PMID 35407580, 2022). "Although the role of IL-5 in autoimmune and parasitic diseases is well described, little is known about its potential involvement in depressive disorder, and the findings have been inconsistent so far." (PMID 36614020, 2022). "It is well established that patients with depression and anxiety have higher plasma levels of C-reactive protein and proinflammatory cytokines (e.g., TNFa, IL-1a, IL-1b, IL-4, IL-5, IL-6, IL-12, and interferon)." (PMID 33802143, 2021). "Conversely, changes in self-reported sleep problems were related to an increase in depression and anxiety (p = 0.001 and p = 0.01 respectively), the T helper 2 (Th2) cytokine IL-5 (p = 0.027), and the counter-regulatory cytokine IL-10 (0.016)." (PMID 33598780, 2021). "There was an improvement in depression levels and a decrease in IL-4 and IL-5 in the IS and in the EBC in both groups." (PMID 34521963, 2021). "In this study, this benefit was evidenced by a reduction in airway inflammatory markers, such as IL-4, IL-5, IL-17A, FeNO and lung function, which consequently resulted in better quality of life and decreased depression levels." (PMID 34521963, 2021). "One strength of our study is that even the CG presented more cough-free days and better IL-4, IL-5, and depression levels after the protocol." (PMID 34521963, 2021). "First, we found that the baseline levels of IL-10, IL-12p70, IL-13, IL-17A, IL-1β, IL-2, IL-23, IL-5, IL-6, IL-7, and MIP-1β were associated with depression symptoms." (PMID 32699226, 2020). "Limited information is available in the literature regarding the role of IL-5 in cancer-related depression." (PMID 32703187, 2020). "Specific differential relationships between IL-5 levels and depression severity were found between patients with breast cancer who were receiving and not receiving chemotherapy." (PMID 32703187, 2020). "We found that the associations between proinflammatory and anti-inflammatory cytokines and depression severity consistently differed between the groups, especially with regard to IL-5." (PMID 32703187, 2020).
depression (continued). "Pro-inflammatory IFN-γ, IL-5 and IL-12 were identified as mediators of the positive prediction of depression severity by the degree of neuroticism." (PMID 30524320, 2018). "Because of the little information on the role of IL-5 in depression, this work in adolescents is the basis for future studies focused on clarifying its involvement in this disorder." (PMID 30662368, 2018). "TNF-α, IFN-γ, IL-5, IL-12, and IL-13 were further related to the severity of depressive symptoms, as well as the somatic-affective and the cognitive dimensions of depression." (PMID 30524320, 2018). "Relative gene expression changes in different inflammatory markers involved in allergic processes (TNFα, IL-1β, IL-4, IL-5, IL-6, and IL-13) were analyzed in the orbitofrontal cortex of suicide completers with a history of major depressive disorder (MDD) versus controls." (PMID 38069051, 2023). "That finding suggested that pro-inflammatory IFN-γ, IL-5 and IL-12 might be identified as mediators of the positive prediction of depression severity by the degree of neuroticism." (PMID 35407580, 2022). "The differences in IL-5 levels and depression symptoms between groups may explain the development of breast cancer; this finding is also supported by the findings of the association between the duration of completion of chemotherapy and cytokine levels." (PMID 32703187, 2020). "Furthermore, differential relationships between IL-5 and depression severity in different groups were also reflected in moderation analyses." (PMID 32703187, 2020). "These associations included: higher IL-6 and IL-8 were associated with a higher incidence of depression at 6 months, TNF-a levels with depression at 12 months, IL-5/IL-8/IL-12/TBF with apathy at 12 months, TNF-a with disinhibition at 12 months, and sVCAM/sICAM/sFAS with depression at 6 months." (PMID 28740480, 2017). "Elevated IL-5, which uses the neural plasticity-related RAS-ERK pathway to mediate its actions in the CNS, could be one of the factors underlying depression-related changes in CNS plasticity." (PMID 22230487, 2012). "Thus, the elevated levels of IL-5 could be one of the factors inducing a depression-related decrease in central nervous system plasticity." (PMID 22230487, 2012). "A possible correlation between these cytokines and depression has been postulated on the basis of the increased genetic risk for major depression associated with the colony stimulating factor 2 receptor β (CSF2RB) haplotype, which encodes a protein in high affinity receptors binding IL-5." (PMID 23046564, 2012). "Furthermore, a gene set analysis of post-mortem brain tissue has suggested that IL-5 levels may be up-regulated in major depression." (PMID 23046564, 2012). "During manic episodes, IL-6, IL-5, interferon (INF)-γ and IL-8 were the upregulated pro-inflammatory cytokines, while only IL-6 was found to be raised during depression." (PMID 38672750, 2024). "Meta-analyses and systematic reviews show that levels of IL-1β, IL-2, IL-4, IL-8, the soluble IL-6 receptor (sIL-6R), IL-5, CCL3, IL-17A, and TGF-β1 are significantly changed in depression." (PMID 36614020, 2022). "Elevated levels of IL-5, which uses the neural plasticity-related RAS GTPase-extracellular signal-regulated kinase (Ras-ERK) pathway to mediate its actions in the central nervous system (CNS), could be one of the factors underlying the depression-related changes in CNS plasticity." (PMID 22230487, 2012). "We observed differential relationships between IL-5 levels and depression in patients with breast cancer who were receiving and not receiving chemotherapy." (PMID 32703187, 2020). "These meta-analyses showed additionally that Th2 and Tregulatory (Treg) cytokines (including IL-10, IL4, and IL-5) were not significantly altered in major depression indicating that major depression is characterized by M1 and Th1 activation." (PMID 29103192, 2018).
depression (continued). "Levels of prenatal cytokines (IL-1, IL-5, IL-7, MPI-1α, GM-CSF, MCP, MIB) were not statistically different when participants were grouped as either low-high stress, yes-no fatigue, or yes-no depression." (PMID 40682534, 2025).